PTH (parathyroid hormone)
Diseases named in the same sentence as PTH in open-access papers (continued):
Sharing a sentence is not in itself a finding about the gene and the disease.
chronic kidney disease (continued). "In contrast to our study and the mentioned studies, another study of 34 children with chronic kidney disease found a correlation between parathyroid hormone and 25(OH)D levels with E’ and E/E’ values." (PMID 40142218, 2025). "Similarly, dysregulation of PTH is a cornerstone of chronic kidney disease-mineral and bone disorder (CKD-MBD), a systemic disorder directly linked to vascular calcification, fractures, and increased mortality risk." (PMID 41414686, 2025). "This process, marked by microfractures and discoloration, is triggered by persistently elevated parathyroid hormone levels in end-stage renal disease (ESRD) patients with tertiary hyperparathyroidism." (PMID 40895913, 2025). "In early-stage chronic kidney disease, compensatory increases in parathyroid hormone (PTH) and fibroblast growth factor-23 (FGF-23) levels maintain serum phosphate within normal ranges by enhancing renal excretion." (PMID 41166265, 2025). "This demonstrates that in chronic renal insufficiency, both trabecular and cortical bone are affected, and that phosphorus effects are direct and indirect, the latter mediated by PTH." (PMID 40573160, 2025). "Accurate measurement of PTH is essential for diagnosing and managing various endocrine and osteological diseases, particularly in the context of chronic kidney disease-mineral and bone disorder (CKD-MBD)." (PMID 41341132, 2025). "For example, chronic elevation of PTH, as seen in secondary hyperparathyroidism associated with chronic kidney disease (CKD), has been shown to disrupt normal feedback regulation of 1α-hydroxylase and, therefore, impaired calcitriol production and associated musculoskeletal complications." (PMID 40787552, 2025). "The whole/intact PTH ratio (w/i PTH) has been demonstrated to correlate with eGFR in stage 3 of chronic kidney disease (CKD3), CKD4, and CKD5, as well as correlating with serum calcium in CKD5." (PMID 40564142, 2025). "Laboratory trends showed increasing proteinuria (>11,000 mg/g), worsening anemia, and rising parathyroid hormone (PTH), consistent with chronic kidney disease (CKD) progression." (PMID 40861755, 2025). "According to some clinical evidence, PTH positively correlates with body fat mass as found in healthy females and males with chronic kidney disease on dialysis." (PMID 40283231, 2025). "Indeed, chronic kidney disease is associated with metabolic bone disease and ectopic calcification via disruption of calcium homeostasis and alterations of physiological calcium regulatory mechanisms, such as abnormal regulation of parathyroid hormone and vitamin D." (PMID 39797166, 2024). "Despite existing findings regarding PTH, creatinine, and urea, there remains much to uncover about the interactions between thyroid function, renal markers, and PTH in chronic kidney disease." (PMID 39484207, 2024). "1-α-hydroxylase, the rate-limiting enzyme pool, is sufficient until end-stage renal disease, claiming PTH and FGF-23 as the principal determinants of calcitriol levels." (PMID 38785509, 2024). "In the context of disease, particularly chronic kidney disease, it is crucial to understand the interplay between vitamin D, the kidneys, and parathyroid hormone (PTH) which constitutes an endocrine loop instrumental in calcium homeostasis." (PMID 38970663, 2024). "PTH stimulates renal calcitriol (1,25D3) synthesis, which promotes reabsorption of calcium and phosphorous, but patients with chronic kidney disease have a reduced ability to produce calcitriol." (PMID 39355148, 2024). "Increased serum P stimulates FGF-23 and PTH, which play a role in cardiovascular disease mortality and hypertension, especially in patients with chronic kidney disease." (PMID 38137499, 2023). "Renal hyperparathyroidism is a common complication of chronic kidney disease characterized by elevated PTH levels secondary to derangements in the homeostasis of calcium, phosphate, and vitamin D." (PMID 37730530, 2023).
chronic kidney disease (continued). "The K/DOQI (National Kidney Foundation Kidney Disease Outcomes Quality Initiative) clinical practice guidelines recommend intact PTH serum concentrations of 150–300 pg/mL for end-stage renal disease (ESRD) and dialysis patients." (PMID 37509715, 2023). "Of note, FGF23 levels are increased in chronic kidney disease even before changes in serum calcium, phosphorous, or PTH levels." (PMID 37627287, 2023). "Our study needs to be supported by prospective, comprehensive studies that include more chronic kidney disease patients; measuring the PTH, lipoprotein A, and homocysteine levels; and standardizing seasonal changes." (PMID 37959300, 2023). "Hip fractures in chronic kidney disease patients typically result due to malnutrition, diminished muscular strength, and decreased bone density, due to vitamin D and parathyroid hormone abnormalities." (PMID 37658363, 2023). "Interacting mechanisms in ARDs, as in chronic renal failure, seem to stimulate not only PTH but also parathyroid gland hyperplasia." (PMID 37841984, 2023). "Cinacalcet, an oral calciomimetic that decrease PTH secretion binding calcium sensing receptor, has been used with success mainly in chronic renal failure patients." (PMID 36998475, 2023). "Subsequent analysis revealed that circulating parathyroid hormone (70 pg/mL), calcium (9 mg/dL, 2.25 mmol/L), and phosphate (4.1 mg/dL) levels were unremarkable considering the level of chronic renal disease." (PMID 36981034, 2023). "In patients with chronic kidney disease, PhA was directly associated with femoral neck BMD, even after considering the effects of age, alkaline phosphatase, intact parathyroid hormone, and LSTM." (PMID 37628307, 2023). "The primary diagnosis of the SHPT patients was 5 chronic kidney disease and medicine had ever been used to control PTH level." (PMID 37051197, 2023). "In the present study, we aim to demonstrate the application of rapid Io-PTH assay in patients with SHPT following chronic kidney disease undergoing parathyroidectomy surgery." (PMID 37231458, 2023). "This bone catabolic effect is seen when PTH blood levels are stably elevated over a long time, for instance, in chronic kidney disease patients." (PMID 36293083, 2022). "Chronic kidney disease (CKD) affects 15% of Americans and greatly increases fracture risk due to elevated parathyroid hormone, cortical porosity, and reduced bone material quality." (PMID 35593150, 2022). "Secondary hyperparathyroidism (SHPT), characterized by overproduction of parathyroid hormone, is a serious complication of patients on maintenance hemodialysis for chronic kidney disease (CKD)." (PMID 35164637, 2022). "Our results showed that CKD patients with moderate-severe PH had higher PTH levels, but the presence of PH has also been reported to be unrelated to the PTH level or the severity of pulmonary artery calcifications in PH patients with chronic renal failure." (PMID 36275815, 2022). "Plasma phosphate levels increase in moderate to advanced chronic kidney disease (eGFR < 60 mL/min/1.73 m2), driven by markedly increased blood levels of phosphate-regulating hormones such as fibroblast growth factor 23 and parathyroid hormone." (PMID 35477475, 2022). "Bone metabolism in children with chronic kidney disease is a triad of biochemical imbalances of calcium, phosphate, parathyroid hormone, vitamin D, bone abnormalities, and soft tissue calcification." (PMID 36405836, 2022). "In PTx for SHPT, complete removal of PTGs is essential to prevent recurrent and persistent SHPT because remnant PTGs in chronic kidney disease can be stimulated and secrete excess intact PTH." (PMID 36419788, 2022). "In patients with chronic renal failure, calcium, phosphorus, parathyroid hormone and 1,25(OH)2D3 have biological interactions that promote and inhibit each other." (PMID 36267284, 2022).
chronic kidney disease (continued). "In primary cultures of parathyroid glands isolated from end-stage renal disease patients, high phosphate increased PTH secretion, parathyroid cell proliferation and COX2 activity." (PMID 35208186, 2022). "CaMg calcium acetate/magnesium carbonate, CKD chronic kidney disease, CV cardiovascular, HD hemodialysis, LC lanthanum carbonate, LV left ventricular, and PTH parathormone." (PMID 36293076, 2022). "In patients with CKD (chronic kidney disease) G5D requiring PTH-lowering therapy, calcimimetics, calcitriol, or vitamin D analogs, or a combination of calcimimetics with calcitriol or vitamin D analogs." (PMID 36595874, 2022). "The role of PTH has been investigated as a traditional biomarker of chronic kidney disease-mineral bone disorder (CKD-MBD) in dialysis patients for decades." (PMID 33514340, 2021). "As seen in advanced renal failure, elevated phosphate levels, together with dysregulated calcium, PTH, and vitamin D levels, contribute to the complex of chronic kidney disease—mineral and bone disease (CKD-MBD)." (PMID 34944233, 2021). "Out of 40 patients with chronic kidney disease, 14 (35%) patients had low PTH levels, 11 (27.5%) had normal PTH levels, and 15 (37.5%) had high PTH levels." (PMID 34322336, 2021). "Intact PTH has a short half-life (approximately 2 min) in patients with normal renal function and approximately 5 min in patients with chronic renal failure." (PMID 33663332, 2021). "During chronic renal failure, patients develop bone mineralization abnormalities due to changes in hormone expression (i.e., PTH, FGF23 and vitamin D) that control mineral homeostasis and osteoblast/-clast function." (PMID 34452102, 2021). "Dysregulation of serum calcium, phosphate, and parathyroid hormone (PTH) begins far before reaching end-stage renal disease, even when kidney function is declined by half." (PMID 35010486, 2021). "Disruption in parathyroid hormone levels (PTH) in patients of chronic kidney disease results in multifaceted complications i.e., pruritus, renal osteodystrophy, neuropathy, cardiac disorders, and vascular calcification, rendering it as uremic toxin." (PMID 34646616, 2021). "In the early stages of chronic kidney disease (CKD), an increase in fibroblast growth factor-23 (FGF23) and parathyroid hormone (PTH) cause a reduction in the tubular resorption of phosphate (P)." (PMID 33498560, 2021). "High serum concentrations of phosphate and linked parameters of phosphorus homeostasis, such as parathyroid hormone (PTH) and fibroblast growth factor 23 (FGF-23), are associated with increased morbidity and mortality in patients with chronic kidney disease." (PMID 34944233, 2021). "A growing number of clinical observations and experimental research involving animals shows that the FGF23 serum level increases significantly in chronic kidney disease much earlier than previously used biomarkers (creatinine, phosphates, vitamin D and PTH)." (PMID 34258392, 2021). "Management of chronic kidney disease mineral and bone disorder requires parathyroid hormone (PTH) concentrations." (PMID 34136780, 2021). "In 2012, the Japanese Society for Dialysis Therapy (JSDT) established the order of correction of P, corrected Ca (cCa), and whole PTH (w-PTH) in the treatment of Chronic Kidney Disease-Metabolic Bone Disorder (CKD-MBD) as P-first." (PMID 34445034, 2021). "Symptoms of SHPT are caused by altered bone metabolism, in which elevated PTH and FGF23 levels, low/normal calcemia, and low 1α,25-(OH)2D variably contribute to the bone alterations defining the chronic kidney disease-mineral bone disease (CKD-MBD)." (PMID 32751307, 2020). "In primary cultures of parathyroids isolated from end-stage renal disease patients, high phosphate increased PTH secretion, parathyroid cell proliferation, and COX2 activity." (PMID 32570711, 2020).
chronic kidney disease (continued). "In clinical practice, assessing parathormone (PTH) concentration is important in exploring calcium/phosphorus metabolism disorders and in monitoring patients suffering from chronic kidney disease." (PMID 32148490, 2020). "In chronic kidney disease (CKD) progressive loss of renal capacity disrupts this axis over‐time, with marked changes in circulating calcium, phosphate, PTH, and fibroblast growth factor‐23 (FGF‐23)." (PMID 33190417, 2020). "In some patients with chronic kidney disease, high serum phosphate was observed in spite of high serum PTH and FGF23 level." (PMID 32398014, 2020). "Improving Global Outcomes (KDIGO) guidelines recommends monitoring chronic kidney disease mineral and bone disorder biochemical markers, including PTH, calcium, phosphorus, and ALP, in patients with moderate-to-severe chronic kidney disease." (PMID 32781868, 2020). "This phenomenon is particularly evident in patients with end-stage renal disease, where carboxy terminal PTH fragments are more abundant than the intact 1–84 PTH form, being half-life of the former (1-2 hours) and very longer than the latter (5–10 minutes)." (PMID 32148482, 2020). "Chronic kidney disease patients have lower levels of 1α,25-dihydroxyvitamin D3, resulting in decreased intestinal calcium absorption, increased parathyroid hormone (PTH) production, and dysregulation of phosphorus metabolism." (PMID 32470067, 2020). "This difference explains the higher PTH values obtained with 2nd generation assays compared with the 3rd generation ones in healthy subjects as well as in subjects with chronic renal failure." (PMID 32148490, 2020). "Because of the effect of reducing PTH synthesis in humans with chronic kidney disease (CKD), calcitriol or analogues have been used to treat secondary renal hyperparathyroidism." (PMID 33287408, 2020). "An elevated parathyroid hormone level and echogenic contracted kidneys on bedside ultrasound in the Emergency department can help differentiate acute kidney injury from chronic kidney disease." (PMID 30993021, 2019). "Accurate measurement of parathyroid hormone (PTH) is crucial for therapeutic decision-making in patients with chronic kidney disease-mineral and bone disorder (CKD-MBD)." (PMID 31637056, 2019). "Overtime chronic kidney disease contributes to development of osteodystrophy and thus increased PTH levels." (PMID 31565143, 2019). "In this context, mineral and bone disorders are common occurrences in chronic kidney disease and are mainly due to abnormalities in serum levels of calcium, phosphorus, and parathyroid hormone (PTH)." (PMID 31846484, 2019). "Health-state descriptions (vignettes) for health states associated with chronic kidney disease (CKD) and a parathyroid hormone condition, secondary hyperparathyroidism (SHPT), were developed based on literature review and a qualitative study involving 54 patients diagnosed with CKD and SHPT." (PMID 31286995, 2019). "Elevated parathyroid hormone levels or echogenic contracted kidneys on ultrasound are known to point to a diagnosis of chronic kidney disease." (PMID 30993021, 2019). "In patients with end-stage renal disease, the reduction of PTH also results in a reduction in serum CPP." (PMID 31241466, 2019). "Chronic kidney disease causes disturbances in the mineral balance and concomitant high levels of plasma FGF23 and PTH." (PMID 29063159, 2018). "Intact PTH has a half‐life of about 2 min in healthy individuals, but in patients with chronic renal failure, iPTH fragments have a degradation time of about 5 min." (PMID 30283905, 2018). "FGF23 and PTH are found to be at elevated levels in chronic kidney disease and end stage renal disease patients in response to elevated phosphate levels." (PMID 30333977, 2018). "It is described by severe skeletal deformities, high level of PTH in patients with chronic renal failure, and deformed face." (PMID 29998151, 2018).
chronic kidney disease (continued). "Another study focusing on the relationship between miRNAs and the PTH level in end-stage renal disease patients demonstrates the close connection between miR-3680-5p and the PTH level." (PMID 30123285, 2018). "It is common that the abnormalities in serum calcium (Ca), phosphorus (P), and parathyroid hormone (PTH) levels appear in patients with moderate and advanced chronic kidney diseases (CKD)." (PMID 28045985, 2017). "Because drastic changes are anticipated in PTH and vitamin D status among subjects with chronic kidney disease, we focused on subjects with relatively preserved renal function." (PMID 28384340, 2017). "Alkaline phosphatase estimation assesses bone turnover in chronic kidney disease patients, especially with elevated PTH levels." (PMID 27335606, 2016). "When the PT hormone becomes less effective (for instance due to chronic renal failure), hyperplasia of the PT glands and increased secretion of PTH develops." (PMID 27875241, 2016). "According to some studies chronic kidney disease (CKD) patients with elevated PTH had a higher level of sST2 compared to HC." (PMID 27900334, 2016). "One concern about parathyroidectomy in kidney transplant recipients is related to the fact that PTH levels remain below the target range as recommended for chronic kidney disease patients in more than half of the cases." (PMID 25861621, 2015). "The Kidney Disease Outcomes Quality Initiative Guidelines recommend parathyroidectomy for patients with chronic kidney disease and parathyroid hormone concentrations exceeding 800 pg/mL; however, this concentration represents an arbitrary cut-off value." (PMID 26064934, 2015). "Although well known for PTH and in the setting of hyperphosphatemia in chronic kidney disease (CKD), only scarce data are available on the effect of acute hyperphosphatemia on FGF-23 levels." (PMID 25790436, 2015). "Elevated PTH contributes probably to the development of uremic cardiomyopathy, considering the correlations between PTH and left ventricular hypertrophy in chronic renal failure." (PMID 26000280, 2015). "The studies cited that argue for a lower threshold for vitamin D levels among African Americans included only healthy adults, and excluded those with chronic kidney disease which is known to alter PTH levels and vitamin D metabolism." (PMID 25734582, 2015). "Clinical studies with chronic kidney disease patients show that different analogs induce a stronger PTH suppression compared to placebo treatment." (PMID 24772087, 2014). "SHPT is a severe and frequent complication in patients with advanced chronic kidney disease, characterized by hyperaplasia of all parathyroid glands and elevated serum PTH levels." (PMID 24886230, 2014). "Probably PTH has a role in the development of uremic cardiomyopathy, suggested by the correlations between PTH level and left ventricular hypertrophy in chronic renal failure." (PMID 24982887, 2014). "The correlation between heart rate variability parameters and PTH serum level indicated the impaired autonomic function in patients with chronic renal failure." (PMID 24982887, 2014). "Parathyroid hormone levels above the upper limit of normal (>65 pg/mL) predicted the future development of end-stage renal disease and the composite outcome of end-stage renal disease or mortality after adjustments." (PMID 23324569, 2013). "Serum concentration of fibroblast growth factor 23 (FGF23) increases in parallel with parathyroid hormone (PTH) as renal function declines in chronic kidney disease (CKD) to maintain phosphate and calcium homeostasis." (PMID 23587028, 2013). "The aim of the present study was to examine the associations between mineral parameters including serum phosphate, PTH and vitamin D and outcomes of end-stage renal disease (ESRD) and mortality in CKD stage 2–4 patients." (PMID 23324569, 2013).